MMP9 (matrix metallopeptidase 9)
Diseases named in the same sentence as MMP9 in open-access papers (continued):
Sharing a sentence is not in itself a finding about the gene and the disease.
minimal change disease (4 papers, 2020 to 2022). "It is known that the MMP-9/NGAL ratio is a better biomarker in the differentiation of MCNS (minimal change nephrotic syndrome) and FSGS in children with nephrotic syndrome than the individual use of each molecule." (PMID 35743361, 2022).
oral epithelial dysplasia (4 papers, 2021 to 2025). "Elevated MMP-9 levels in the saliva of subjects with oral epithelial dysplasia are detectable even in mild and moderate instances, with an increase related to disease advancement." (PMID 39911325, 2025). "Salivary MMP-9 concentrations are notably higher in severe oral epithelial dysplasia, attributed to the increased likelihood of malignant transformation in these patients." (PMID 39911325, 2025). "Studies have reported overexpression of MMP-2 and MMP-9 in oral epithelial dysplasia (OED), with MMP-9 expression correlating significantly with OED grade in patient samples." (PMID 36428690, 2022). "MMP9 has shown significantly higher levels in patients with OSCC than in those with premalignant oral lesions (OPMD) as well as those in the control group." (PMID 36330456, 2022). "Among all these studies, only two groups examined the diagnostic value of MMPs: using the ROC analysis, Ghallab showed serum MMP-9 with an AUC of 0.6, which failed to differentiate between oral SCC and oral premalignant lesions." (PMID 34266392, 2021).
osteoclastoma (4 papers, 2019 to 2020). "Increased MMP9 activity has been implicated in many diseases including osteoclastomas, Paget's disease, bone fracture repair and dental pulp inflammation." (PMID 33144645, 2020). "In human osteoclastoma cells, curcumin inhibits cell proliferation and promotes apoptosis through JNK, NF-κB and MMP-9 signaling pathways." (PMID 31505816, 2019).
Pain (4 papers, 2018 to 2025). An unpleasant sensory and emotional experience associated with actual or potential tissue damage, or described in terms of such damage. "In summary, MMP-9 plays a key role in the onset and progression of various types of peripheral neuropathic pain." (PMID 41245602, 2025). "It is reported that MMP9 is upregulated in the DRG of a mouse model of neuropathic pain." (PMID 37304762, 2023).
pelvic organ prolapse (4 papers, 2013 to 2025). Abnormal descent of a pelvic organ resulting in the protrusion of the organ beyond its normal anatomical confines. "To verify whether C-1562T MMP9 polymorphism could be responsible for more severe genital prolapse cases, we have stratified the assessment and analyzed patients with a complete absence of prolapse (stage 0) versus patients with total prolapse (stage IV)." (PMID 30939607, 2019). "According to unvariable analyses, statistically significant association was noted between positive immunoreactivity to MMP-1, MMP-2, and MMP-9 in the round ligaments and the occurrence of pelvic organ prolapse." (PMID 40607267, 2025). "Mice deficient for the fibulin-5 gene (Fbln5−/−) develop pelvic organ prolapse (POP) due to compromised elastic fibers and upregulation of matrix metalloprotease (MMP)-9." (PMID 23437119, 2013). "Vaginal distention in Fbln-5-/- mice has been shown to induce activity of proteases (MMP2 and MMP9) in vaginal tissue, but increased production of other SASP cytokines unique to pelvic organ prolapse in mice has not yet been completely elucidated." (PMID 39331015, 2024).
pemphigus (4 papers, 2021 to 2025). Pemphigus is a group of rare autoimmune diseases that cause blistering of the skin and mucous membranes (mouth, nose, throat, eyes, and genitals).This conditioncan occur at any age, but often strikes people in middle or older age. "IgG/IgA pemphigus showed higher expression of IL-8 and MMP-9 in the epidermis than conventional pemphigus." (PMID 35625932, 2022). "In contrast, the epidermal expression of MMP-9 was significantly higher in patients with IgG/IgA pemphigus." (PMID 35625932, 2022). "Despite the relatively limited number of studies investigating the role of MMPs in autoimmune blistering diseases, inactivation of ADAM10 and MMP-9 were shown to prevent blister formation in experimental models of pemphigus and pemphigoid, respectively." (PMID 34680139, 2021). "Supporting this, certain investigations have demonstrated elevated epidermal expression of IL-8 and MMP-9 in IgG/IgA pemphigus patients compared to traditional pemphigus cases, potentially explaining the more severe clinical manifestations associated with IgG/IgA co-deposition." (PMID 40491920, 2025).
pneumococcal meningitis (4 papers, 2007 to 2020). An acute purulent infection of the meninges and subarachnoid space caused by Streptococcus pneumoniae, most prevalent in children and adults over the age of 60. "B7-H3 enhanced the inflammatory response and promoted MMP-9 expression in a pneumococcal meningitis animal model." (PMID 27145365, 2016). "Based on our earlier studies with TACE inhibitor TNF484 in neonatal rat pneumococcal meningitis, we first confirmed that TNF484 used at 1 mg/kg twice daily blocked TNF and MMP-9 in CSF of infected mice." (PMID 17428319, 2007).
polycystic kidney (4 papers, 2020 to 2024). "The scan of the older child, who also had a LoF mutation in MMP9, exhibited pyelectasis (a soft marker), while that of the younger one showed a polycystic kidney (a structural anomaly)." (PMID 39350038, 2024). "Comparison of jck-MMP9+/+ and jck-MMP9-/- mice led us to show a protective role of MMP9 in the pathology of polycystic kidney disease and to uncover a new substrate of MMP9." (PMID 38039285, 2023). "We have shown that MMP9 protects from apoptosis, and it is known that both ILK and activation of FAK regulate cell proliferation in polycystic kidney disease." (PMID 38039285, 2023). "Several studies on polycystic kidney disease have revealed cystic kidneys tubules synthesize and secrete high levels of MMPs, especially MMP-2, MMP-1 and MMP-9." (PMID 33256255, 2020).
polyp (4 papers, 2021 to 2023). A usually exophytic mass attached to the underlying tissue by a broad base or a thin stalk. "Insufficient suppression of MMP‐9 by TIMP‐1 in polyp could lead to degradation of ECM, and hence, pseudocyst formation." (PMID 33900049, 2021). "There was no MMP-2 and MMP-9 mRNA expression in polyp of vocal cord tissues." (PMID 31882379, 2021).
Polypoidal choroidal vasculopathy (4 papers, 2013 to 2022). The presence of aneurysmal 'polypoidal' lesions in the choroidal vasculature. "However, increases in MMP2 and MMP9 were correlated with polypoidal choroidal vasculopathy, suggesting potentially different underlying mechanisms from AMD." (PMID 36498929, 2022). "A systemic imbalance of MMP-9 and TIMP-1, thought to reflect an imbalance of the extracellular matrix homeostasis, is previously associated with polypoidal choroidal vasculopathy (PCV) in Asian patients." (PMID 32429088, 2020).
pulmonary embolism (4 papers, 2016 to 2024). The obstruction of the pulmonary artery or one of its branches by an embolus, sometimes associated with infarction of the lung. "The relationship between MMP-9 and NGAL is also studied in the context of arterial aneurysm rupture and patients with pulmonary embolism." (PMID 39199360, 2024). "In previous studies, MMP-9 and PAI-1 levels have been shown to be beneficial for the diagnosis of suspected pulmonary embolism." (PMID 27042667, 2016).
retinopathy of prematurity (4 papers, 2017 to 2023). A bilateral retinopathy characterized by neovascularization, scarring, retinal detachment, and eventually blindness. "Levels of THBS1, MMP8, MMP9, MMP25, TIMP2 and TIMP3 increased as severity of BPD and retinopathy of prematurity (ROP) increased, whereas ETS1, LEF1 and SPOCK2 exhibited the opposite trend." (PMID 28103583, 2017).
rhabdomyosarcoma (4 papers, 2013 to 2023). A rare aggressive malignant mesenchymal neoplasm arising from skeletal muscle. "Additionally, in context to rhabdomyosarcoma cases, upregulations of CDH1 (epithelial marker), SLUG (inducer of EMT), and MMP9 (matrix-modifying enzyme) are reported." (PMID 37503316, 2023). "Rhabdomyosarcoma showed MMP-2 and faint MMP-9 bands; PMA treatment enhanced MMP-9 expression." (PMID 23900236, 2013).
rheumatic disease (4 papers, 2010 to 2023). "Thus, the MMP-3 to MMP-1 ratio, and levels of TIMP-3, MMP-9, andosteopontin could be prognostic markers for AoDILD in collagen diseases." (PMID 23405989, 2013). "Our findings that GTH inhibit the activity of MMP-9 suggest the potential effect of GTH in mitigating the destruction of cartilage and inflammation of rheumatic diseases." (PMID 21054849, 2010).
scleroderma (4 papers, 2008 to 2026). Scleroderma is a rare autoimmune connective tissue disorder characterized by abnormal hardening of the skin and, sometimes, other organs. "The MMP9 risk genotype did not correlate with scleroderma-specific autoantibodies, while the NOS3 GG genotype was associated with lower serum levels of anti-collagen IV antibodies (p = 0.039)." (PMID 41596747, 2026).
seminoma (4 papers, 2019 to 2026). A radiosensitive malignant germ cell tumor found in the testis (especially undescended), and extragonadal sites (anterior mediastinum and pineal gland). "MMP9 is expressed in seminomas, and exposure of the TCam‐2 cell line to activin A results in increased MMP9 transcript levels." (PMID 40693358, 2026). "The higher levels of neutrophil markers and MMP9 in area 2 of the seminoma sample compared with area 1 in the present study highlights the presence of two distinct microenvironments." (PMID 40693358, 2026). "A recent study demonstrated co-localization of the macrophage marker CD68 and the metalloproteinase MMP9 in seminomas." (PMID 39684459, 2024). "Moreover, our work reveals spatial heterogeneity in the distribution of T cells with different functional states in tumors, while macrophages in seminoma can participate in extracellular matrix degradation through the secretion of MMP9 and CTSK." (PMID 38123589, 2023). "To further examine the functions of MMP9 and CTSK in seminoma, we subset immune cells (PTPRC+), and explored the expression patterns of markers for T cells (CD3D+ and CD3E+) and B cells (CD79B+; MS4A1+ and SDC1+)." (PMID 38123589, 2023). "Further investigation are needed to extend the number of clinical cases investigated, to analyze the co-localization of PTTG1 with MMP2, MMP9, VEGF and to clarify if a functional abrogation of PTTG1 might represent a novel therapeutic approaches in the clinical management of seminoma." (PMID 31572301, 2019).
serous ovarian cancer (4 papers, 2016 to 2025). "On the basis of these findings, we used immunohistochemistry to assess MMP-9 expression in our series of high- and low-grade serous ovarian cancers." (PMID 27462782, 2016). "While high MMP-2 and MMP-9 expression have been associated previously with neo-angiogenesis and tumor vascularization, an increase in protein expression of MMP-9 correlated with an increase in patient’s death rate diagnosed with high-grade serous ovarian cancer." (PMID 35047406, 2021). "In addition, increased expression levels of MMPs, including MMP-2, MMP-7, and MMP-9, as well as TIMPs, including TIMP-1 and TIMP-2, were observed in mucinous ovarian cancer compared with those in serous ovarian cancer." (PMID 32197606, 2020). "Similarly, a study on serous ovarian cancer cell lines demonstrated that PIK3R1 downregulation induced the expression of antiapoptotic BCL2, as well as genes involved in cell cycle progression (CCNB1) and metastasis (MMP9 and VEGFA)." (PMID 39858051, 2025).
Shock (4 papers, 2015 to 2021). The state in which profound and widespread reduction of effective tissue perfusion leads first to reversible, and then if prolonged, to irreversible cellular injury. "Treatment of AE-IPF or septic shock with PMX-DHP has also been reported to decrease the concentrations of serum matrix metalloproteinase (MMP)-9, vascular endothelial growth factor (VEGF), and angiopoietin-2, which can facilitate vascular permeability." (PMID 25887940, 2015). "In a clinical study of patients with septic shock, MMP-9 levels in nonsurvivors were higher than those in survivors and healthy controls." (PMID 33488296, 2021).
synovitis (4 papers, 2021 to 2025). Inflammation of a synovial membrane. "Compared with the KOA group, the synovitis ointment group, the KOA + Western medicine group, and the KOA + Chinese medicine group significantly decreased the expression of SDF-1, CXCR4, MMP-9, and MMP-13." (PMID 35815270, 2022). "To unravel the effects of synovitis ointment on SDF-1/CXCR4, we examined the expression of SDF-1, CXCR4, MMP-9, and MMP-13 in serum under different treatment conditions through the ELISA method." (PMID 35815270, 2022). "After applying with synovitis ointment, the expression levels of SDF-1, CXCR4, MMP-9, and MMP-13 reduced significantly in KOA rats." (PMID 35815270, 2022). "Consistent with our prior analyses, wherein lower MMP-9 was consistent with the Inflamma-type, MMP-9 was negatively correlated with the effusion-synovitis score, but this result was not significant (p=0.52)." (PMID 37214045, 2023).
thymic lymphoma (4 papers, 2018 to 2022). "Further, EGF-dependent EGR1 upregulation inhibits the growth of thymic lymphoma by suppressing MMP9 production from stromal cells." (PMID 30845713, 2019). "While there is ample evidence on the role of MMP-9 in promoting thymic lymphoma growth, less is known about the effects of MMP-9 on normal T-cell function." (PMID 30500835, 2018).
thymoma (4 papers, 2022 to 2024). A neoplasm arising from the epithelial cells of the thymus. "Our research screened out the core target genes AKT1, MMP9, STAT3, SRC, and EGFR of thymoma-associated M, and carried out molecular docking verification." (PMID 37498332, 2024). "MMP-2 and MMP-7 are predominantly expressed in type B3 thymoma and thymic carcinoma, while MMP-9 is preferentially expressed in B2 thymomas." (PMID 38201593, 2023). "Interestingly, the expression of MMP-9 was higher in the normal tissues of thymoma than in tumor tissues." (PMID 35178444, 2022).
transient ischemic attack (4 papers, 2022 to 2025). A brief attack (from a few minutes to an hour) of cerebral dysfunction of vascular origin, with no persistent neurological deficit. "This study aimed to explore the clinical study of clopidogrel combined with Huoxue Tongluo prescription in improving transient ischemic attack (TIA) and the effect on MMP-9, Hcy, and CRP." (PMID 35399851, 2022). "An ex vivo study using human carotid plaques obtained from patients with transient ischemic attacks revealed that oleacein could suppress plaque instability by attenuating related biomarkers such as HMGB1 and matrix metalloproteinase-9 (MMP-9)." (PMID 36768748, 2023).
Ureteral obstruction (4 papers, 2016 to 2025). Obstruction of the flow of urine through the ureter. "Inhibition of MMP-9 activity reduced kidney fibrosis in murine unilateral ureteral obstruction." (PMID 27130612, 2016).
urinary tract infection (4 papers, 2018 to 2025). "Abedi and Mohammadjafari postulated that urinary MMP-9 and TIMP-1 may be markers of renal scarring in children with urinary tract infections." (PMID 32670438, 2020). "Levels of urinary MMP-9 of participants, general and without urinary tract infection, according to renal impairment status." (PMID 30564523, 2018).
uveitis (4 papers, 2010 to 2022). An inflammatory process affecting a part of or the entire uvea. "We have determined that several of these genes (e.g., CCL4, Jun, and MMP9) are likely to be important for the pathogenesis of uveitis." (PMID 28505077, 2017). "Vitreous MMP-2 was not significantly different between the IOL group (2.3 ± 0.79 ng/ml) and the uveitis group (2.5 ± 0.58 ng/ml, P = 0.42), whereas vitreous MMP-9 was significantly lower in the IOL group (1.0 ± 1.07 ng/ml) than in the uveitis group (8.3 ± 7.04 ng/ml) (P < 0.05)." (PMID 36357882, 2022). "One important molecule involved in uveitis that is modulated by TNF-α is MMP-9." (PMID 29302691, 2018). "Vitreous MMP-2 levels were not elevated in either the IOL and uveitis groups in this study, whereas vitreous MMP-9 levels in the uveitis group were significantly higher than in the IOL group." (PMID 36357882, 2022). "Vitreous MMP-9 was significantly higher in the uveitis group than in the IOL without extraocular involvement group (P < 0.05)." (PMID 36357882, 2022). "Although the mechanism of sIL-2R elevation in uveitis is still unknown, MMP-2 and MMP-9 may be involved in the migration of lymphocytes in uveitis as well as IOL." (PMID 36357882, 2022).
Vertigo (4 papers, 2019 to 2022). An abnormal sensation of spinning while the body is actually stationary. "In previous studies, we found that a high level of plasma MMP-9 was associated with basilar arteriectasia in dizziness or vertigo patients." (PMID 35518204, 2022). "In vertigo patients, we found various probably associations between MMP-9 and TIMP-1 with arterial alterations linked to both VBD and WMH that may help with the diagnosis and treatment of such diseases in the future." (PMID 31474817, 2019). "MMP-9 serum level was significantly higher in vertigo patients with VBAs dilation and basilar artery (BA) elongation compared to those with healthy arterial size, and the ratio of MMP-9/TIMP-1 level were higher in those patients." (PMID 31474817, 2019). "We found that MMP-9 serum level was higher in vertigo patients with VBA dilation and BA elongation, and the ratio of MMP-9/TIMP-1 level were higher in those patients, while TIMP-1 serum level was higher in those patients with BA tortuosity." (PMID 31474817, 2019). "MMP-9 and TIMP-1 serum levels were both higher in vertigo patients with VBD, and we further found that upregulation of MMP-9 might be accompanied by the downregulation of TIMP-1 but not by TIMP-2 regulation." (PMID 31474817, 2019).
visceral leishmaniasis (4 papers, 2013 to 2024). A severe form of leishmaniasis characterized by irregular bouts of fever, substantial weight loss, swelling of the spleen and liver, and anemia (which may be serious). "Furthermore, in canine visceral leishmaniasis high levels of serum MMP-9 is associated with multi-systemic inflammatory lesions." (PMID 23870715, 2013). "In the skin of dogs with visceral leishmaniasis, increased levels of matrix metalloproteinases, especially MMP-9, have been observed." (PMID 38787223, 2024). "However, the role of MMP-9 and sCD40L has not been explored in human visceral leishmaniasis." (PMID 23870715, 2013).